GZMB (granzyme B)
Diseases named in the same sentence as GZMB in open-access papers (continued):
Sharing a sentence is not in itself a finding about the gene and the disease.
tumor (continued). "These HLA-DR+ CTLs produce IFN-γ and Granzyme B, enlightening their effector and probable anti-tumor activity profile." (PMID 30555458, 2018). "T cell cytotoxicity was mediated via granzyme B release and mediated enhanced tumor control in vivo." (PMID 30214445, 2018). "It represses CTL-mediated tumor cytotoxicity by altering the expression of perforin, granzyme A, granzyme B, Fas ligand (FASL), and IFNγ." (PMID 29486723, 2018). "Tumor-infiltrating lymphocytes were further characterized by immunohistochemical staining for granzyme B, which marks activated effector lymphocytes." (PMID 29468364, 2018). "Targeting autophagy by knocking down Beclin1 in hypoxic tumor cells was sufficient to rescue the granzyme B level in hypoxic cells and restore NK-mediated lysis." (PMID 29922284, 2018). "In our knowledge, this is the first time that we describe a subpopulation of neutrophil expressing GZMB with an anti-tumor ability." (PMID 29983866, 2018). "Tumour regrowth was associated with decreases in CD8+ T cells, NK cells, and loss of granzyme B and IFNγ production, confirming dampened inflammation." (PMID 30327563, 2018). "To investigate the immune microenvironment, we then analyzed the frequencies of CD8+ T cells and the activated granzyme B+ subset of CD8+ T cells in each of the tumor samples using multicolor immunofluorescence." (PMID 29761158, 2018). "Noteworthy, the apoptotic tumor cells, contiguous to neutrophils, contain GZMB, suggesting that lipid A induces neutrophil GZMB release that contributes to cancer cell demise." (PMID 29983866, 2018). "Alteration of granzyme B function in tumor cells decreased the cytotoxic effect of Lipid A in rat and mouse models." (PMID 29983866, 2018). "Overall, we provide strong evidence for the involvement of GZMB produced by neutrophils in immuno-induced tumor regression, widening the field of tumor immunotherapy mechanisms." (PMID 29983866, 2018). "Using GFP granzyme B-expressing NK cells, we provided evidence that the level of granzyme B is significantly lower in hypoxic tumor cells compared with normoxic tumor cells." (PMID 29922284, 2018). "This enhanced tumor killing activity of T cells is also supported by increased levels of granzyme B and IFNγ in the media." (PMID 30324091, 2018). "CD27 molecules expressed on the surface of NK cells can bind to CD70 molecules on the surface of tumor cells to transduce activation signals and enhance the expression and release of perforin and granzyme B and promote the killing activity of NK cells." (PMID 29643992, 2018). "We have reported that autophagy activation in tumor cells impaired NK-mediated killing by selective degradation of NK-derived granzyme B in the lysosome compartment." (PMID 29922284, 2018). "Within the tumor draining lymph node, we observed significant decreases in granzyme B expression within the CD4+ compartment in the involution group, with granzyme B restored upon ibuprofen treatment." (PMID 30285905, 2018). "Very consistently, there are elevated anti-tumor molecules such as perforin, granzyme B, CTSE and increased Th1 transcription factor T-bet while decrease of Th1 inhibitory molecule like SOCS1 and Twist1 in the lung of CD4-Chi3l1 KO mice." (PMID 29403003, 2018). "The combination also promoted IFNg, IL12 and granzyme B production in the tumor microenvironment and decreased the formation of liver metastasis in a very early phase of tumor development, enabling 90% survival." (PMID 30356111, 2018). "c and fraction of tumor border CD8 T cells positive for granzyme B (Gzm B) and tumor border CD4 T cells positive for Foxp3." (PMID 30285905, 2018). "Of interest, B cells stimulated by IL-21 are able to kill tumor cells by producing granzyme B. B cells also facilitate CD4+ T cell memory function and CD8+ T cells proliferation." (PMID 29850009, 2018).
tumor (continued). "Pre-vaccination blood CD8+ T cell count and ELISPOT Granzyme B production capacity in vitro upon tumor antigen exposure were significantly correlated with overall survival." (PMID 30518425, 2018). "After combined treatment, most tumor-infiltrating lymphocytes were granzyme B positive, which was also the case in the two tumors that regressed in the IL-12 monotherapy group." (PMID 29468364, 2018). "Here, we demonstrated that AZD1775, a small molecule inhibitor of WEE1 kinase, prevented granzyme B-induced G2/M cell cycle checkpoint activation and sensitizes tumor cells to NK killing." (PMID 29925431, 2018). "CD8 and Granzyme B are surface antigens of cytotoxic T lymphocytes (CTLs) that are the main effective cells in the anti-tumor immune response." (PMID 28915679, 2017). "Limited anti-tumor efficacy studies have suggested that the targeted delivery of the human pro-apoptotic molecule Granzyme B to tumor cells has significant potential for cancer treatment." (PMID 28714916, 2017). "The anti-EGFR CAR-T cells secreted cytokines including IL-2, IL-4, IL-6, IFN-γ, TNF-α, GM-CSF, and granzyme B in co-culture with EGFR-positive tumor cells." (PMID 28356156, 2017). "Type-I NKT cells can directly destroy tumor cells, especially those expressing CD1d on their surface, by performing cytolysis via perforin, granzyme B, Fas ligand (FasL), and TRAIL." (PMID 29354122, 2017). "To evaluate the effect of HBZ on tumor development and bone loss in vivo, we generated transgenic mice expressing HBZ under the Granzyme B promoter (Gzmb-HBZ)." (PMID 29050201, 2017). "TGF-β inhibits T cell-mediated tumor clearance in vivo by specifically inhibiting the expression of five cytolytic gene products, including perforin, granzyme A, granzyme B, Fas ligand, and IFN-γ, in CTLs30." (PMID 28687760, 2017). "The breadth of responses includes anti-tumor effector (Granzyme B, IFN-γ, MIP-1α, TNF-α), stimulatory (GM-CSF, IL-2, IL-8), regulatory (IL-4, IL-13, IL-22), and inflammatory (IL-6, IL-17A) functions." (PMID 29157295, 2017). "The studies of immune-related gene expression in tumor tissue also included genes involved in T-cell activation and cytolytic activity, such as granzyme B or perforin." (PMID 29034210, 2017). "When 4T1 tumor cells were added to naïve neutrophils we observed increased granzyme-B release compared to neutrophils alone (adj." (PMID 28143493, 2017). "Most tumors can induce adaptive immune responses, and the presence of a higher number of IFN-γ- and granzyme B+-producing lymphocytes in tumor tissues correlates with better prognosis." (PMID 27935862, 2017). "The presence of anti-tumor CD8+ T cells within a tumor can be a positive prognostic factor which correlates with the presence of intratumoral granzyme B, IFN-γ and IL-2, hallmarks of cytolytic CD8+ T cell responses." (PMID 29072624, 2017). "Tumor-infiltrating T cell activation status was assessed by granzyme B (left) and perforin (right) staining." (PMID 28967558, 2017). "This study also reported an increase in IFN-γ and granzyme B expression and a three-fold increase in tumor-infiltrating cytotoxic leukocytes in mice receiving IL-10." (PMID 29137411, 2017). "This included more anti-tumor immune profiles, including increased density of iNOS+ cells and Granzyme B+ cells with MMP-14 blockade." (PMID 28938563, 2017). "This is supported by a significantly higher amount of perforin and granzyme B transcripts in Klrk1+/+ than Klrk1−/− liver tissue surrounding tumours." (PMID 28128200, 2017). "This is confirmed by functional data indicating an enhanced recruitment of granzyme B+ effector lymphocytes by IL-15 DCs, as compared to IL-4 DCs, and subsequent superior killing of tumor cells by the migrated lymphocytes." (PMID 28099143, 2017). "This protein is known to protect tumor cells from apoptosis by binding and inactivating the cytotoxic granzyme B (GrB) molecules released by the immune-related cytotoxic cells." (PMID 28423701, 2017).
tumor (continued). "Of note, among the NK cells isolated from MHC class I-deficient tumours, Tim-3+ PD-1+ NK cells exhibited a dramatically reduced expression of effector molecules such as IFN-γ, CD107a, granzyme B and perforin compared with their Tim-3−PD-1− counterparts." (PMID 28585539, 2017). "Infiltration of CD3+ T cells and Granzyme B+ effector cells was significantly increased in MT/Shc2F/2F tumours (P<0.0001 by Mann–Whitney U-test)." (PMID 28276425, 2017). "We detected an expansion of tumor-specific T lymphocytes 7 days after virus administration and a strong induction of granzyme B on NK cells 14 days after virus administration." (PMID 28029653, 2017). "Serpin B9 (Protease Inhibitor-9) would normally protect immune cells present in a tumor micro-environment from T-cell or NK-cell misdirected granzyme B, but have also been found to be upregulated in several tumor types as an immune evading mechanism." (PMID 28895912, 2017). "Accordingly, expression of NK cell functional markers (i.e., CD107a, IFN-γ, granzyme B, and perforin) was significantly reduced on NK cells by incubation with iC3b-containing serum, following the stimulation with K562 tumor cells." (PMID 29209332, 2017). "CD4+ T cells can directly kill MHC class II positive tumor cells in a perforin/granzyme B cell-dependent manner and can indirectly eliminate tumor cells that lack expression of MHC class II by cytokine-mediated activation of macrophages." (PMID 28428886, 2017). "Quantification of GZMB signal intensities in MC from tumor section confirmed the DC101-induced increase of GZMB in MC." (PMID 28814715, 2017). "In mice receiving Rik-overexpressing CD8+ T cells, TNF-α and granzyme B levels in tumor implants were less than those in mice receiving control CD8+ T cells." (PMID 28382040, 2017). "Adding the induced Tregs strongly inhibited proliferation of CTLs in response to tumor lysate-pulsed autologous DCs in proportion to the numbers of Tregs added, and markedly reduced their perforin and granzyme B levels." (PMID 28290464, 2017). "Similar to the observation in the tumour model, effector memory CTLs were the major population and had the highest expression of perforin and granzyme B in the target tissues of the GVHD model, indicating their roles in GVHD pathogenesis." (PMID 28537251, 2017). "IL-21, a member of the γc family, has also been reported to improve CD8+ T-cell function through regulation of IFN-γ, granzyme B and perforin production, and survival in infection and tumour models." (PMID 28798332, 2017). "CAR OT-I cells not only recognized target tumor cells and secreted cytotoxic granule proteins (perforin, granzyme B) but also induced serial killing which were observed in real time via time-lapse microscopy." (PMID 28356156, 2017). "Increased levels of killer cell activity markers in the TME (IFN-γ, granzyme B and perforin) were also observed in tumours treated with combination therapy." (PMID 28345650, 2017). "In contrast, WASp KO NK cells showed reduced capacity to accumulate F-actin and granzyme B towards the lytic synapse interface with YAC-1 tumor cells." (PMID 27477778, 2016). "In order to investigate in situ the effect of propranolol on anti-tumor cytotoxicity, we assessed the presence of granzyme B by immunohistochemistry." (PMID 27788481, 2016). "Cytoplasmic granules within CTL and NK cells release Granzyme B that induce apoptosis within virus-infected cells or tumor cells." (PMID 27824136, 2016). "EBI3 blocking peptide promoted antitumor cytotoxic T lymphocyte (CTL) response by inducing Granzyme B, IFN-γ production, and p-STAT3 expression and inhibited CRC cell proliferation and tumor growth to associate with suppressing gp130 and p-STAT3 expression." (PMID 27247488, 2016). "In preclinical models, treatment with IMM-101 appeared to increase the secretion of IFNγ and cytotoxic mediators such as perforin and granzyme B at the tumor site, the draining lymph nodes and in the spleen in tumor-bearing mice." (PMID 27141395, 2016).
tumor (continued). "Here, we observed a significant increase of CD8+ T-cells with a higher expression of granzyme B in the primary tumor stroma of propranolol-treated mice, suggesting a better activation of these cells." (PMID 27788481, 2016). "Granzyme B (GzmB) is a key cytotoxic molecule utilized by T cells to kill pathogen-infected cells or transformed tumor cells." (PMID 27774524, 2016). "In contrast, there was a significant decrease in granzyme B expression, which is an important protease that facilitates augmented tumor angiogenesis." (PMID 27075020, 2016). "Our previous report with syngeneic tumor models indicated that GzmB is critical for the ability of CD4+CD25+ regulatory T (Treg) cells to suppress antitumor immune responses mediated by CD8+ cytotoxic T cells and natural killer (NK) cells." (PMID 27774524, 2016). "In the IMCG cohort for example, CD28 and CD3 with aging decreased expression of GZMA and GZMB, proteases important in T cell and NK-cell-mediated tumor cell lysis." (PMID 27760559, 2016). "For example, in tumor cell killing, NK cells release perforin and granzyme B as effector molecules, with the perforin-forming pores in the tumor cell membrane, thereby allowing entrance of granzyme B to activate caspases and induce target cell death." (PMID 28123389, 2016). "Our study revealed that HSP70-P/AFP-P vaccination elicited significant cytotoxicity of NK cells against H22 or Hepa1-6 tumor cells through granzyme B and perforin release." (PMID 27713135, 2016). "It has also been proposed that cisplatin pretreatment increases the permeability of tumour cells to granzyme B secreted by effector cells." (PMID 26931556, 2016). "GzmB has been known as a key cytotoxic molecule used by cytotoxic lymphocytes to kill host cells infected by intracellular pathogens or transformed tumor cells." (PMID 27774524, 2016). "The IFN-γ, TNF-α, NO levels in splenocytes supernatant, as well as iNOS, IFN-γ, Granzyme B mRNA levels in splenocytes and tumor blocks were significantly increased." (PMID 27246354, 2016). "Particularly, EBI3 blocking promoted tumor infiltrating Granzyme B+ CTLs and IFN-γ+ CTLs production and restrained CRC cell proliferation through bidirectional reciprocal-regulation STAT3 signaling pathway." (PMID 27247488, 2016). "Analysis of infiltrating granzyme B+ cells at the invasive borders of the tumor revealed an even greater difference by race (p<0.001)." (PMID 27310868, 2016). "While much remains to be learned mechanistically, these data highlight that the degradation of GZMB by autophagy during its intracellular trafficking constitutes a novel mechanism of tumor escape from NK-mediated killing." (PMID 26910842, 2016). "These tumor-infiltrating T cells are also activated by radiation since effector molecules such as perforin, granzyme B, and FasL are all high in the radiation-treated tumor than in untreated control tumors." (PMID 27014915, 2016). "In prostate cancer, the tumor-associated MDSCs potently inhibit autologous CD8+T cells proliferation and production of IFN-γ and granzyme-B, thereby impairing anti-tumor immunity." (PMID 27458169, 2016). "To further determine the cytotoxicity of GIFT4-CLL cell-primed T cells, we performed intracellular staining of cytotoxic factors perforin and granzyme B, and surface staining of tumor-killing molecule CD314 (NKG2D) on those T cells." (PMID 27118475, 2016). "In mouse tumor model, such as colon cancer, IL-27 strengthens anti-tumor activity by supporting production of perforin and granzyme B from CD8+ T cells, in addition to the promotion of proliferation and IFN-γ production." (PMID 25633106, 2015). "It is worth noting that EI-05 administration also remarkably enhanced the production of IFNγ and Granzyme B by tumor-infiltrated CD8+ T cells." (PMID 25796556, 2015). "Apoptotic nuclei, presumably from tumor cells, were evident in the vicinity of Granzyme B+ lymphocytes." (PMID 26291724, 2015).
tumor (continued). "Meanwhile, RT-PCR data showed that the expression of CCL5 and CXCL10 was positively correlated with the local expressions of the CD8+ T lymphocyte markers (CD8 and Granzyme B) in tumor tissues." (PMID 26317795, 2015). "Even patients whose tumours showed a pCR had significantly suppressed levels of granzyme B+/perforin+ NK cells (47.50 ± 8.00), when compared with HFDs (60.26 ± 2.50) (p = 0.032)." (PMID 26040463, 2015). "Although the mean mRNA expression of granzyme B in the tumor tissues was higher than that of normal breast tissue, the difference was not significant." (PMID 25605488, 2015). "The frequency of CD8+ T cells was significantly higher in tumor tissue than normal breast tissues while granzyme B expression was similar." (PMID 25605488, 2015). "Granzyme B+ cells were very scarce in tolerated xenografts, and if found, these cells were in or around tumor microvessels." (PMID 26291724, 2015). "The effects of 8-Br-ADPR were confirmed by confocal microscopic findings that 8-Br-ADPR blocked the tumor cell-induced translocation of perforin and granzyme B towards the immunological synapse between B16F10 and NK cells." (PMID 25879940, 2015). "In vitro stimulation of murine and human iNKT cells with α-GalCer led to an enhanced lysis of tumor cells in a perforin- and granzyme B-dependent fashion, which suggested a direct protective role of these cells in tumor lysis." (PMID 26029217, 2015). "The reduced level of NK cell granzyme B/perforin expression was more significantly inhibited in those patients whose tumours had a partial or poor pathological response to NAC." (PMID 26040463, 2015). "Despite this, similar frequency of granzyme B mRNA expression levels in the tumor and the normal tissues indicated that CD8+ T cells in the tumors were not active." (PMID 25605488, 2015). "It was previously reported that the classical chemotherapeutic agents paclitaxel, cisplatin, and doxorubicin sensitize several types of solid tumor cells to cytotoxic T-lymphocytes by increasing tumor cell permeability to granzyme B." (PMID 25393910, 2015). "We were intrigued by a reversal of tumor-induced downregulation of effector genes perforin, granzyme B and eomesodermin in the spleens and LN of tumor-bearing mice treated with bortezomib." (PMID 26431276, 2015). "In the complete response (CR) cases, 999 overexpressed genes including at least 234 tumor-specific CTL-activation associated genes such as IFNG, PRF1, and GZMB, were found in post-treatment biopsy specimens." (PMID 26625258, 2015). "It is reported that GrB-expressing B cells (granzyme B+ Bregs) reside within the microenvironment of different tumor types." (PMID 26378021, 2015). "Granzyme-B-dependent cytolysis and B7-H1/PD-1 pathway contribute to immune suppression in the tumor microenvironment." (PMID 25768730, 2015). "Compared to non-memory cells, the memory cells of XBP1-CTL demonstrated significantly greater anti-tumor activities, measured by granzyme B upregulation and IFN-γ production." (PMID 27668268, 2015). "It showed that GZMB, which is a key anti-tumor molecule in vivo, was regulated mainly by miR-199a-5p and miR-199b-5p." (PMID 25826780, 2015). "NK cells treated with 8-Br-ADPR, an ADPR antagonist, as well as NK cells from Cd38−/− mice showed reduced tumor-induced granule polarization, degranulation, granzyme B secretion, and cytotoxicity of NK cells." (PMID 25879940, 2015). "To confirm the inhibitory effects of 8-Br-ADPR on the translocation of intracellular perforin and granzyme B to the plasma membrane in response to tumor cell contact, we examined the subcellular distributions of perforin and granzyme B by Western blot." (PMID 25879940, 2015). "Previously, our group described biochemical and structural variability of NPM1 in tumor and differentiating cells, indicated by differences in epitope exposure, granzyme B recognition and resistance to SDS denaturation." (PMID 25490769, 2014).